CCL5 (C-C motif chemokine ligand 5)
Diseases named in the same sentence as CCL5 in open-access papers (continued):
Sharing a sentence is not in itself a finding about the gene and the disease.
tumor (continued). "Nevertheless, in a mouse model of PDAC, knockdown of CCR5 from tumor cells resulted in suppression of tumor growth and significant decrease of Tregs in the TME, suggesting that the CCL5/CCR5 pathway has an impact on the infiltration of Tregs." (PMID 35404390, 2022). "To expand our findings of CCL2 and CCL5 regulated by lncSNHG5-ZNF281 signaling in promoting tumor metastasis, we evaluated CCL2 and CCL5 levels in tumor tissues and serum CCL2 and CCL5 of healthy donors and BC patients with or without metastasis." (PMID 36438499, 2022). "Natural human AML cells can generate CCL5 and express CCR5, and the CCL5/CCR5 axis can promote tumorigenesis by regulating the tumor microenvironment." (PMID 35280440, 2022). "Our study firstly revealed the positive correlations between NLRC3 and CCL5 and CXCL9 expressions in HCC, which explained the mechanisms of NLRC3-related CD8+ T cell infiltration in tumor." (PMID 35145917, 2022). "At the same time, TAN-N2 presents an anti-inflammatory profile, exhibiting higher levels of CD184 (CXCR4), arginase-1, CCL2, CCL5, VEGF, IL-8, and MMP-9, supporting tumor growth, invasion, and metastasis." (PMID 35741003, 2022). "CCR5 usually appears in pools or as small dots on the surface of tumor cells, when CCR5 becomes activated by chemokine C–C Ligand 5 (CCL5) (e.g., RANTES)." (PMID 35327389, 2022). "Immature DCs can be recruited into the TME, attracted by tumor-secreted factors such as CCL2, CCL20/MIP3a, CCL25, CCL5, CXCL12, CXCL1, and CXCL5, while mature DCs reside in areas surrounding the tumor." (PMID 35267487, 2022). "Like in the primary tumor, CCL2 was increased in wounded mice (p < 0.05) and there was a trend for an increase in CCL5 (p = 0.06)." (PMID 36325601, 2022). "In vitro and in vivo data demonstrated that ATRi plus RT promoted the production of CCL3, CCL5, and CXCL10 in tumour cells." (PMID 35365161, 2022). "CD40 engagement on HRS cells increased both tumor growth and survival, upregulated CD54, CD80, and IRF4 expression, augmented the secretion of IL-8, TNF-α, IL-6, LT-α and CCL5, decreased Fas-mediated apoptosis and increased NF-kB activation." (PMID 35626032, 2022). "XCL1 is mostly secreted by tumor-resident CD56low NK cells, CCL4 and CCL5 are primarily generated by CD56low and CD56high NK cells, and CD8+ T cells are all part of this profile." (PMID 36703982, 2022). "MDSCs, a heterogeneous population of immature myeloid cells, are recruited into the tumor by various chemokines CCL1, CCL2, CCL5, or CXCL5." (PMID 35741103, 2022). "Subsequently, we analyzed DEGs between tumor and normal tissues and selected the top five DEGs with the highest expression, which were SPP1, AKR1C2, AKR1B10, AGT, and EPHX1 in tumor tissues and NKG7, KLRD1, KLRB1, CCL5, and CST7 in normal tissues." (PMID 35967424, 2022). "CCL5 secreted by lymphocytes promotes the proliferation of CRC cells capable of expressing CCR5, thereby promoting tumor growth in liver metastatic lesions." (PMID 36387070, 2022). "It has been reported that Ccl5 can induce the infiltration of CD8+ T cells 55, CD4+ T cells 56, and NK cells 31 into the TME, thereby enhancing the anti-tumor immune responses." (PMID 36438484, 2022). "CCL5 binds to CCR5 and has been shown to direct the mobilization of PMN-MDSCs from bone marrow to blood for tumor progression." (PMID 35267547, 2022). "As a cytokine secreted by T lymphocytes, macrophages, and some other cells, CCL5 can regulate the expression and secretion of normal T cells and bind with CCR5 (C-C chemokine receptor type 5) to recruit anti-tumor T cells and dendritic cells to TME." (PMID 35145917, 2022). "Regulatory T cells (Treg), a sub-population of CD4+ T cells capable of downregulating anti-tumor immune responses, are induced by MDSC in the periphery and are attracted to the tumor site by secretion of the chemokines CCL4 and CCL5." (PMID 35455309, 2022).
tumor (continued). "CCL5 and EGF can induce tumor cell invasion by promoting IL-8 secretion from tumor cells via Akt signaling activation." (PMID 35936717, 2022). "Among the molecules activated by STING signaling, IFNs can stimulate the generation of anti-tumor T cells, T-cell infiltration and the direct killing of cancer cells, whereas CXCL10 and CCL5 are important for recruiting tumor-reactive effector T cells." (PMID 36498833, 2022). "During hyperthermia, cells under heat stress enhance immune response by promoting the release of more exosomes rich in tumor antigens, chemokines (including CCL2, CCL3, CCL4, CCL5 and CCL20, etc.)and HSP to APC to identify and destroy tumor cells." (PMID 36032103, 2022). "As one of the critical members of TME cellular components, tumor-associated macrophages (TAMs) perform an indispensable function in the tumor resistance link and can be recruited to the tumor localization by CCL2, CCL5, and CAFs." (PMID 35953863, 2022). "Blocking the CCL5/CCR5 axis induced decreased endothelial cell migration, which was related to decreased activity of the mTOR /Akt pathway, while CCL5 promoted tumor angiogenesis through the PKC δ/c-Src/HIF-1 α/VEGF signaling pathway." (PMID 35784750, 2022). "In turn, activated adipocytes secrete chemokines (CCL2, and CCL5), cytokines (IL-1β, IL-6, TNF-α), and angiogenic factors (VEGF), all required for the promotion of tumor growth, angiogenesis and metastasis." (PMID 35493456, 2022). "Th17 cells are generated by tumor-derived IL1β and IL13, and accumulate in tumor tissues in response to various chemokines, including CCL2, CCL5, CCL20, CCL17, CCL22, and MIF, which are produced from tumor cells." (PMID 36211375, 2022). "It seems that promoted numbers of CTLs in tumor tissue, as evidenced in previous study, rely on the improved expression of T cell-attracting chemokines (CXCL9, CXCL10, and CCL5) as shown in colon cancer MC38 cell bearing mice upon oxaliplatin treatment." (PMID 34980128, 2022). "Lysate from MTP-treated tumors showed an even stronger upregulation of chemokines involved in immune cell recruitment, including CXCL9, CCL5, CXCL10, CD40 and CXCL16, compared to both control and MTX-treated tumor lysates." (PMID 36397148, 2022). "Next, the expression of CCL5 was detected in human CRC tissues using IHC, and the results showed that CCL5 was highly expressed in tumor buds at the invasive front." (PMID 35241150, 2022). "Activated platelet membrane nanovesicles, which retain almost all of the platelet-proteins, target tumor tissues through P-selectin and CD44, and mediate neutrophil recruitment through P-selectin, ICAM-2, and CCL5." (PMID 36034656, 2022). "We also examined mRNA expression of Ccl5 and Cxcl10, two major target genes downstream of STING activation that recruit cytotoxic T lymphocytes to the tumor." (PMID 36443299, 2022). "In a previous study, CCL5 was found to interact with CXCL9 expressed by macrophages, leading to an increase in T cell infiltration and inhibition of tumor progression." (PMID 36428599, 2022). "We found that 47 genes were upregulated in tumor tissues compared to normal tissues, such as CD48, TIGIT, GNLY, CCL19, CCL5, CXCL13, CCL17 and NKG7." (PMID 36713530, 2022). "Particularly, in addition to the tumor immune escape pathway, genetic markers belonging to the cytokines/interleukins, including CXCL8, CCL5, CCR5 and angiogenic mediators including IGF1, IRF3, NOS2, appear to be the most promising." (PMID 36432658, 2022). "Tumor cells and MDSCs in the TME are able to secrete CCL3, CCL4, and CCL5, interacting with CCR5 on Tregs and attracting them into the TME." (PMID 35345849, 2022). "A mouse model revealed the importance of eosinophils in improving the infiltration of CD8+ T cells into the tumor by CCL5, CXCL9 and CXCL10 production, thus referring to their active participation in tumor rejection." (PMID 35565423, 2022).
tumor (continued). "PDX9228 and PDX4582 tumors exhibited high expression of CCL5 and CXCL5, respectively, two cytokines shown to mobilize MDSCs from the bone marrow and infiltrate at the tumor site." (PMID 36551639, 2022). "In turn, by secreting CCL5 and CCL17/TARC, HRS cells recruited T lymphocytes and then educated them to become exhausted/anergic T cells that supported tumor cell survival." (PMID 35626032, 2022). "Monocytes are recruited to the tumor by chemokines such as CCL2, CCL5, CCL7, CCL8, CXCL12, VEGF, and M-CSF, and become TAMs." (PMID 35565420, 2022). "The mRNA and secreted protein levels of CCL5 were examined in FHC and eight human CRC tumor cell lines, and the results were entirely consistent with initial findings from the co-culture recruitment assay." (PMID 35241150, 2022). "Adipocytes and BC tumor cells release chemokines (e.g., C-C motif chemokine ligand 2 (CCL2), C-C motif chemokine ligand 5 (CCL-5), or colony-stimulating factor (CSF-1)) to promote the migration of monocytes and macrophages into the BC microenvironment." (PMID 36364213, 2022). "The results of tumor purity showed that three cytokines (CCL5, CCL19 and CXCL9) were negatively correlated with tumor purity, which indicated that tumor cells were reduced but immune cells increased in tissues with high expression of these cytokines." (PMID 35359417, 2022). "To study the functional roles of these T cell-recruiting chemokines, we used neutralizing antibodies to antagonize the expression of CCL5, CXCL9, and CXCL10 in JQ-1-treated tumor-bearing mice." (PMID 35292660, 2022). "TNBC-derived IL6 induces CCL5 expression in stromal lymphatic vessels of the lung and lymph nodes through STAT3-AP1 signaling, resulting in tumor extravasation and colonization." (PMID 36612175, 2022). "By secreting wide range of cytokines and chemokines, such as CCL3, CCL5, CCL22 and TGFβ, TAMs participate also in the recruitment of regulatory T cells (Treg) to the tumor microenvironment and suppress cytotoxic T cell functions." (PMID 35493456, 2022). "Subsequently, the up-regulation of CCL5, CXCL10, and IFN-γ in LLC tumor tissues was confirmed by real-time PCR." (PMID 35002511, 2022). "CXCL9 can bind to CXCR3 expressed in tumor cells to recruit CD4 + T cells, thus promoting the production of CCL5 in TME, promoting tumor invasion." (PMID 36159780, 2022). "Differentially expressed cytokines (CCL5, CCL19, CXCL9 and CXCL10) were related to the overall survival, and their expression levels were also examined both in tumor tissues of CL-BCa patients by IHC and in typical CL-BCa cell lines by qPCR." (PMID 35359417, 2022). "In ccRCC samples with CCL5 upregulation, the proportion of CCL5+ TAMs and PD-L1+ CD68+ TAMs were prominently increased, showing a typical suppressive tumor immune microenvironment (TIME)." (PMID 35982911, 2022). "We detected more abundant levels of sICAM-1, CXCL10, CXCL1, CCL5, TIMP-1 and TNFα in tumours treated with VV-αCEA TCE, compared to tumours treated with VV-CTRL or PBS." (PMID 36405739, 2022). "ATC-like tumor shows high levels of T cell infiltration, chemo-cytokines (CCL2, CCL3, CCL4, CCL5, CXCL9, and CXCL10), and immune checkpoints." (PMID 36293435, 2022). "The expression levels of other hub genes CTLA4, CXCL10, CCL5, CCl4, ICAM1, CXCL9, CD27, GZMB, FCGR2A, SELL, IDO1 in SKCM were higher than those in non-tumor skin tissues (P < 0.05), and the results were statistically significant." (PMID 35710862, 2022). "CCL5 and CCR5 are overexpressed in colorectal cancer (CRC) primary tumor cells as well as in metastasis cells of the liver and lung and are positively correlated with prognosis in CRC." (PMID 35702353, 2022). "Growth factors such as HGF, VEGF, EGF, CTGF, IGF, and NGF, cytokines such as IL-6, IL-11, and IL-17, and chemokines such as CCL7, CCL5, CXCL12, and CXCL7 are produced by CAF in the process of interaction between tumor cells and CAF." (PMID 36293435, 2022).
tumor (continued). "Lysates of MTX-treated 9464D tumors displayed a more than 2.5-fold increase of IL1a, CXCL16, FLT3L, CX3CL1 and IL1RA, and a more than 1.5-fold increase of CXCL10, CXCL5, CCL5 and CXCL9 compared to control tumor lysates." (PMID 36397148, 2022). "These chemokines can be secreted by the tumor itself (e.g., CCL4, CCL5, XCL1) or by other infiltrating immune cells." (PMID 36230990, 2022). "M-MDSCs are recruited to the TME primarily by tumor-derived CCL2 and CCL5, while PMN-MDSCs are recruited by CCL2 and CCL3." (PMID 35345849, 2022). "It is reported that CAFs secrete CCL2, CCL5, CCL7, and CXCL16 chemokines into the tumor microenvironment, promoting the HCC cells invasion and metastasis by activating either hedgehog or TGF-β pathways." (PMID 35589690, 2022). "The increased secretion of CCL5 from CRC cells can also promote the apoptosis of CD8+ T cells via regulatory T cells, thereby promoting tumor progression via immunosuppression." (PMID 35241150, 2022). "Previous studies have suggested that many chemokines (CCL5 and CCL2) and cytokines (the VEGF family members and CSF‐1) can be able to recruit circulating inflammatory monocytes to the tumor environment, exerting an enormous effect on the formation of TAMs." (PMID 35593325, 2022). "More specifically, we have detected increased levels of sICAM-1, CXCL10, CXCL1, CCL5, TIMP-1 and TNFα in tumours treated with VV-αCEA TCE, compared to tumours treated with VV-CTRL or PBS." (PMID 36405739, 2022). "First, hypoxia‐triggered release of chemoattractants (i.e., CCL2, CCL5, CXCL12, CSF‐1, and VEGF) from tumor cells and non‐tumor cells to enhance TAMs precursor monocytes recruitment." (PMID 37323705, 2022). "In vivo, significant modulation of cytokine gene expression (particularly CCL2 and CCL5, and C-X-C motif chemokine ligand 10) was observed, with in vitro data indicating that CCL2, CCL5, and CXCL10 were produced by tumor cells after ATR inhibition plus RT." (PMID 36612206, 2022). "Similarly, we hypothesized that the chemokines CCL2 and CCL5—which are pro-metastatic chemokines that promote tumor cell invasion and act mainly through the Gαi-signaling receptors CCR2 and CCR5, respectively —also contribute to increased invasion of WT-PD-L1-MDA cells." (PMID 35205789, 2022). "A quantitativestudy on tumor inflammation-related mRNA expression revealed inductionsof key gene expressions, such as STAT1, CXCL10, CCL5, and CCL2, andrejuvenation of TME with enhancement in T cell, macrophage, NK cell,chemokine, and cytokine functions." (PMID 36153998, 2022). "Results of qRT-PCR partially demonstrated the bioinformatics results that the mRNA levels of CXCL10, CXCL9, CCL5, and CCR2 were remarkably elevated in tumor tissues collected from PTC patients coexistent with HT than those without HT." (PMID 36266640, 2022). "The possibility of targeting a tumor and its TME with chemokines via the CCL5/CCR5 axis is promising, and new therapeutical technologies are under investigation." (PMID 36430633, 2022). "CCL2, CCL3, CCL5, and CCL7 attract monocytes/macrophages to exert anti-infective, anti-tumor, and immunomodulatory effects at sites of inflammation." (PMID 36188003, 2022). "So NLRC3 high expression represents a novel predictor for positive survival outcomes in HCC patients, and NLRC3 is involved in CD8+ T cell infiltration, which is correlated with increased CCL5 and CXCL9 in TME (tumor microenvironment)." (PMID 35145917, 2022). "Our study provides more comprehensive insights into the role of CCL5 in CRC progression and elucidates the comprehensive tumor–microenvironment interaction network in CRC." (PMID 35241150, 2022). "Multiple studies have shown that the STING signaling pathway affects tumor development through secretory proteins such as CXCL10, CCL5, and IFNs." (PMID 36496076, 2022).
tumor (continued). "TXA2 signalling was also shown to activate the endothelium, promoting tumour cell survival by mediating the recruitment of pro-metastatic monocytes in proximity to tumour cells through the release of the chemotactic factors CCL2/MCP-1 and CCL5." (PMID 36558983, 2022). "Fourth, despite the impressive promotion in tumor immunity, the roles of the four chemokines-CXCL9, CXCL10, CXCL11, and CCL5-in tumorigenesis and progression were still in debates." (PMID 35692828, 2022). "We found that CCL5 expression has a significantly strong positive linear relationship with the PI3K/AKT signaling pathway and a tumor proliferation signature (Spearson's correlation value = 0.44 and 0.39, respectively, P<0.0001)." (PMID 35982911, 2022). "Several studies have shown that CCL5 and CCL8 promote cancer cell proliferation and migration as well as the recruitment of T regulatory cells, which leads to tumor progression." (PMID 35954489, 2022). "For instance, NK cells recruit type 1 dendritic cells to the tumor and promote T1 cell polarization through the release of CCL2, CCL3, CCL4, CCL5, XCL1, and CXCL8, thus inducing anti-tumoral protection." (PMID 35565420, 2022). "Therefore, CCL5 is a key chemokine that determines whether a tumor will be infiltrated by T cells." (PMID 35145917, 2022). "NMU overexpression in HT29 cells induced or increased the secretion of tumour supporting cytokines (CXCL1/GROa, CXCL10/IP-10 and ICAM-1/CD54, CCL-5/RANTES, IL-8 and IL-1ra)." (PMID 36482448, 2022). "Recently, it has been reported that CDK4/6i can also induce metabolic stress in tumor cells, leading to expression of chemokines such as CCL5 and CXCL10 that can further enhance anti-tumor immune responses." (PMID 35248122, 2022). "In the TME, CAFs-secreted CCL2, CCL5, CCL17, IL-1, IL-6, IL-13, and IL-26 can also promote a Th2 and Th17 CD4+ polarization, at the expense of anti-tumor Th1 response." (PMID 36338519, 2022). "The capacity of MSCs to move toward tumor tissue is also mediated by other factors, such as chemokines CCL2, CCL5, CXCL16, diffusible cytokine IL-8, as well as growth factors IGF1, PDGF, VEGF, and TGF-β." (PMID 36324128, 2022). "Except for NOS1, DNMT1 and CCL5, the hub genes CCL19 and CCR7 in DE-GRGs are compose of the CCL19/CCL21-CCR7 axis that exerts both immune response and tumor proliferation." (PMID 35517412, 2022). "Consistent with this, the expression of T cell chemokine genes such as CCL3, CCL4, CCL5, CXCL9, CXCL10 and CXCL1123 in MKN74 tumours tends to be higher than that in other tumours, especially after ERY974 administration." (PMID 36071036, 2022). "Results of qRT-PCR partially demonstrated the bioinformatics results that the mRNA levels of CXCL10, CXCL9, CCL5, and CCR2 were remarkably elevated in tumor tissues collected from PTC patients coexistent with HT than those without HT (P < 0.001)." (PMID 36266640, 2022). "In the previous study, the co-expression of CCL5 and CXCL9 has been detected to reveal immunoreactive tumours with prolonged survival and response to PD-1 inhibition." (PMID 35865633, 2022). "Inside the TME, Prostaglandin E2 (PGE2) inhibits CCL5 and XCL1 production and leads to reduced NK cell viability, highlighting that the TME can interfere with NK cell-mediated anti-tumor functions through multiple mechanisms." (PMID 36372017, 2022). "IL5, IL9, CCL5, GM-CSF, and CCL28 expression by HRS cells helps recruit them to the affected lymph nodes, while eosinophils can enhance the proliferation of tumor cells by different mechanisms, such as CD30L secretion." (PMID 35267668, 2022). "We then analyzed tumor-infiltrating CD4 T cells and found an increased expression of interferon-beta (Ifnb1) and interferon-stimulated gene (ISG) transcripts (Ccl5, Ifit1, and Mx2) in cells isolated from mice treated with cGAMP compared with controls." (PMID 35091453, 2022).